LEKR1 (leucine, glutamate and lysine rich 1)
Synonyms: FLJ16641
Tractability: PROTAC: ubiquitination databases record sites on it.
Gene: Protein-coding gene on chromosome 3 (156,825,481 to 157,046,129, forward strand). Ensembl gene ENSG00000197980.
Subcellular location (Human Protein Atlas): Nucleoplasm; Nucleoli
Genetic constraint (gnomAD): Loss-of-function variants: 14 observed, 18.06 expected, observed/expected ratio (o/e) 0.78, 90% interval 0.51 to 1.21. The upper end of that interval is the gene's LOEUF score, 1.21, which puts it in group 5 of 6, group 1 being the genes least tolerant of losing a copy. Missense variants: 379 observed, 389.38 expected, observed/expected ratio (o/e) 0.97, 90% interval 0.89 to 1.06. Synonymous variants: 155 observed, 144.05 expected, observed/expected ratio (o/e) 1.08, 90% interval 0.94 to 1.23.
Homologues: Orthologues: chimpanzee LEKR1 (99% identical), macaque LEKR1 (96% identical), dog LEKR1 (84% identical), pig LEKR1 (83% identical), rabbit LEKR1 (81% identical), mouse Lekr1 (75% identical), rat Lekr1 (72% identical), tropical clawed frog lekr1 (41% identical).
Diseases named in the same sentence as LEKR1 in open-access papers:
LEKR1 is named in the same sentence as 4 diseases in open-access papers, as found by Europe PMC text mining. Sharing a sentence is not in itself a finding about the gene and the disease. The quoted sentences say what the papers report.
gallstones (1 paper, 2025). Solid crystalline precipitates in the biliary tract, usually formed in the gallbladder, resulting in the condition of cholelithiasis. "For instance, although the fSFA‐decreasing alleles of rs603424 and rs67261871 (LEKR1) were associated with cardiometabolic protection, they also increased circulating MUFAs and reduced the degree of unsaturation—profiles that have been implicated in hepatic steatosis and gallstone formation." (PMID 41024449, 2025).
LEKR1 also shares sentences with these, for which no sentence is quoted: Hepatic steatosis (1 paper); metabolic syndrome (1); ovarian carcinoma (1).